RBM17 (RNA binding motif protein 17)
Diseases named in the same sentence as RBM17 in open-access papers:
RBM17 is named in the same sentence as 28 diseases in open-access papers, as found by Europe PMC text mining. Sharing a sentence is not in itself a finding about the gene and the disease. The quoted sentences say what the papers report.
papillary thyroid cancer (10 papers, 2021 to 2025). "For instance, MAP4K4 mRNA was reported to be alternatively spliced in papillary thyroid cancer samples by RBM17, which causes phosphorylation of downstream signaling pathways." (PMID 36977901, 2023). "In papillary thyroid cancer, the 33-nt GlyGCC 5′tRNA half is upregulated and directly binds to RBM17 protein to induce alternative splicing of MAP4K4 mRNA, thereby showing tumor-promoting effects." (PMID 37430089, 2023). "A recent study identified that tiRNA-Gly promotes the proliferation and migration of papillary thyroid cancer cells by binding to RNA binding motif protein 17 (RBM17), a spliceosome protein that can selectively splice mRNAs." (PMID 36761955, 2023). "Papillary thyroid cancer (PTC) samples exhibit elevated levels of a 33-nt-GlyGCC 5′tRNA half, which binds to the UHM domain of RBM17 and promotes the translocation of RBM17 to the nucleus." (PMID 37430089, 2023). "In papillary thyroid carcinoma (PTC), highly expressed tiRNA-Gly can directly bind to RNA binding motif protein 17 (RBM17) and lead to RBM17-dependent phosphorylation of downstream signaling pathways by inducing mitogen-activated protein kinase 4 (MAP4K4) mRNA exon 16 splicing." (PMID 35658952, 2022).
ovarian carcinoma (7 papers, 2019 to 2023). A malignant neoplasm originating from the surface ovarian epithelium. "In addition, RBM17 has been previously linked to cancer chemotherapy resistance in breast and ovarian cancer cell lines through unspecified mechanisms." (PMID 35781533, 2022).
hypopharyngeal carcinoma (4 papers, 2021 to 2025). Carcinoma, predominantly squamous cell, arising from the epithelial cells of the hypopharynx. "In summary, our findings prove that RBM17 is highly expressed in hypopharyngeal cancer and is associated with poor prognosis." (PMID 36941989, 2023). "It has been reported that RBM17 knockdown enhances the sensitivity of hypopharyngeal cancer cells to CDDP." (PMID 40243905, 2025). "Overexpression of RBM17 inhibited the sensitivity of human hypopharyngeal cancer cells to cisplatin and promote cell invasion." (PMID 37962768, 2023). "More work and experiments are needed subsequently to further reveal the mechanism of action of RBM17 in hypopharyngeal cancer." (PMID 36941989, 2023). "The expression of RBM17 in hypopharyngeal cancer tissues was verified by qRT-PCR and western blot, and it was found that RBM17 was highly expressed in hypopharyngeal cancer tissues." (PMID 36941989, 2023). "Our previous studies have shown that RBM17 can affect the migration, invasion ability, and cisplatin sensitivity of hypopharyngeal cancer cells." (PMID 36941989, 2023). "In our previous studies, it has been demonstrated that knockdown of RBM17 can inhibit the proliferation of FaDu cells in hypopharyngeal cancer." (PMID 36941989, 2023). "This suggests that knockdown of RBM17 can inhibit EMT progression in hypopharyngeal cancer." (PMID 36941989, 2023). "Knockdown of RBM17 inhibits growth of hypopharyngeal carcinoma cells." (PMID 34804951, 2021). "On this basis, this study revealed for the first time the functional role of RBM17 in the regulation of cisplatin sensitivity, migration, invasion, and EMT of hypopharyngeal cancer cells and its downstream-related molecular mechanisms." (PMID 36941989, 2023). "However, no study has reported the effects of RBM17 on drug resistance, cell migration, and invasion in hypopharyngeal cancer." (PMID 36941989, 2023). "However, whether the EMT process of hypopharyngeal cancer cells is related to RBM17 has not been reported in the previous literature." (PMID 36941989, 2023).
leukemia (3 papers, 2022 to 2024). A malignant (clonal) hematologic disorder, involving hematopoietic stem cells and characterized by the presence of primitive or atypical myeloid or lymphoid cells in the bone marrow and the blood. "Previous studies have demonstrated that RNA-binding proteins (RBPs) were frequently mutated in leukemia patients and essential for leukemia growth and differentiation, such as RBM17 and RBM39 in AML." (PMID 38216972, 2024). "Together, these studies suggest that RBM17 knockdown leads to NMD of genes involved in leukemia propagation." (PMID 35781533, 2022). "Studies have shown that high expression of RBM17 in hematological tumors can promote the progression of leukemia and may be related to drug resistance of leukemia." (PMID 36941989, 2023).
prostate carcinoma (3 papers, 2016 to 2025). A carcinoma that arises from epithelial cells of the prostate gland. "Taken together, given its small size yet excellent predictive power, we concluded [AQP1, SEPT8, RBM17, TRIM47, VPS25] as a novel, practical biomarker panel for predicting response to 17-AAG treatment in prostate cancer." (PMID 36743211, 2023).
glioma (2 papers, 2021 to 2023). A benign or malignant brain and spinal cord tumor that arises from glial cells (astrocytes, oligodendrocytes, ependymal cells). "RBM17 functions in promoting cell proliferation, affecting the cell cycle, and inducing apoptosis in human glioma cells." (PMID 34804951, 2021).
hepatocellular carcinoma (2 papers, 2020 to 2025). A malignant tumor that arises from hepatocytes. "However, the role of the AS factor RBM17 in the progression of hepatocellular carcinoma (HCC) has not yet been elucidated." (PMID 40702000, 2025).
viral infection (2 papers, 2021 to 2022). "Differentially expressed genes in the viral infection category (174 genes) indicated that keratinocytes had down-regulated genes involved in host gene transcription (DDX56, SMARCA2) and RNA transportation and processing (NUP98, RAE1, XAB2, RBM17, EXOSC10)." (PMID 34552595, 2021).
autoimmune disease (1 paper, 2022). A disorder resulting from loss of function or tissue destruction of an organ or multiple organs, arising from humoral or cellular immune responses of the individual to their own tissue constituents. "Irrespective of this, two candidate causal SNPs and genes including rs3087243 (RAPH1) and rs61839660 (IL2RA, RBM17, PFKFB3, LINC02649) were found to be common between T1D and other autoimmune diseases." (PMID 35773720, 2022).
glioblastoma (1 paper, 2021). The most malignant astrocytic tumor (WHO grade IV). "Silencing RBM17 induced the pro-apoptotic exon 6 inclusion splicing switch in the FAS gene; as well as cell cycle arrest and apoptosis in glioblastoma cells in vitro and decreased tumor growth in a glioblastoma xenograft model in vivo, which makes it an interesting target for treatment." (PMID 34065983, 2021).
liver cancer (1 paper, 2023). An epithelial or non-epithelial malignant neoplasm that arises from the liver. "In terms of tumor research, RBM17 can promote the proliferation of tumor cells in liver cancer cells and is associated with poor prognosis, so it can be used as a potential therapeutic target for liver cancer." (PMID 36941989, 2023).
lung carcinoma (1 paper, 2024). "To further elucidate the mechanism by which MSI2 and RBM17 induce radioresistance in lung cancer cells, we performed immunofluorescence detection of MSI2 and RBM17 in A549 cells at 0, 0.5, 4, 8, 12, and 24 h post‐irradiation with 8 Gy." (PMID 38645664, 2024). "Scientific hypothesis: After radiation exposure, lung cancer cells undergo DNA damage, triggering RBM17 to sense signals." (PMID 38645664, 2024). "We first found that knockdown of RBM17 produced radiosensitization of lung cancer cells." (PMID 38645664, 2024). "When lung cancer cells undergo DNA damage after radiation exposure and emit certain signals, RBM17 may sense these signals, translocate into the nucleus, facilitate the entry of MSI2, and subsequently interact with ATR, activating ATR along with CHK1 and other downstream molecules." (PMID 38645664, 2024). "Based on the experimental results presented above, we posit that MSI2 enhances DNA damage repair through interactions with RBM17 and ATR, thereby increasing the radiation resistance of lung cancer cells." (PMID 38645664, 2024). "We found that knockdown of RBM17 disrupted the interaction between MSI2 and ATR post‐irradiation and increased the radiosensitivity of lung cancer cells." (PMID 38645664, 2024). "RBM17 and MSI2 may synergistically promote radioresistance in lung cancer." (PMID 38645664, 2024). "When lung cancer cells are irradiated after knocking down MSI2, there is not enough MSI2 to enter the nucleus after DNA damage occurs, and it cannot interact with RBM17 and ATR to activate ATR, resulting in DNA damage repair not proceeding smoothly." (PMID 38645664, 2024). "When MSI2 is knocked down or inhibited in lung cancer cells, there is not enough MSI2 to enter the nucleus after DNA damage, so it cannot interact with RBM17 and ATR to activate ATR, which will not successfully complete DNA damage repair and increase tumor cell death." (PMID 38645664, 2024).
myeloid leukemia (1 paper, 2022). A clonal proliferation of myeloid cells and their precursors in the bone marrow, peripheral blood, and spleen. "To understand the molecular mechanisms that underlie the supporting role of the splicing factor RBM17 in AML, we first performed RBM17 enhanced crosslinking immunoprecipitation (eCLIP)-seq in the K562 myeloid leukemia cell line to identify genome-wide RNA targets bound by RBM17." (PMID 35781533, 2022).
oral cancer (1 paper, 2025). "We also examine the potential of RBM17 as a therapeutic target for oral cancer." (PMID 40243905, 2025). "After exposing oral cancer cell lines to fluorouracil (5-FU) and cisplatin, but not paclitaxel, the gene and protein expression of RBM17 increased." (PMID 40243905, 2025).
spinocerebellar ataxia type 1 (1 paper, 2016). Spinocerebellar ataxia type 1 (SCA1) is a subtype of type I autosomal dominant cerebellar ataxia (ADCA type I) characterized by dysarthria, writing difficulties, limb ataxia, and commonly nystagmus and saccadic abnormalities. "A pathological poly-glutamine expansion in ATXN-1, causally related to spinocerebellar ataxia type 1 (SCA1), e.g., was found to induce binding of the protein to RBM17 rather than CiC, thereby promoting disease." (PMID 27200083, 2016).
cancer (16 papers, 2015 to 2025). A tumor composed of atypical neoplastic, often pleomorphic cells that invade other tissues. "RBM17 is expressed at low levels in normal tissues, yet is frequently overexpressed in various cancers." (PMID 40243905, 2025). "We propose the underlying mechanism that RBM17 promotes CHEK1 protein expression in the ATM/ATR pathway, triggering the development of chemoresistance in cancer cells." (PMID 40243905, 2025). "The expression level of RBM17 was greatly elevated in carcinoma tissue compared to that in para-carcinoma tissue." (PMID 40702000, 2025). "Knockdown of RBM17 significantly inhibits cancer-cell proliferation and arrested cells in the G2/M phase." (PMID 40636922, 2023). "Through a series of phenotypic experiments, we found that knockdown of RBM17 inhibited the migration and invasion of cancer cells." (PMID 36941989, 2023). "In our previous studies, we found that knockdown of RBM17 can inhibit the proliferation of cancer cells by inducing FaDu cell cycle arrest and apoptosis using flow cytometry." (PMID 36941989, 2023). "We systematically collected expression data for RBM17 in 12 types of cancer and 3 queries from the Cancer Genome Atlas (TCGA) and Gene Expression Omnibus (GEO) databases." (PMID 32497093, 2020). "Several studies have demonstrated that RBM17 is responsible for chemoresistance in cancers." (PMID 40243905, 2025). "Importantly, RBM17 confers resistance to doxorubicin and vincristine, two chemotherapeutic drugs commonly used in cancer treatment." (PMID 36743211, 2023). "It was found that FaDu cells treated with IC50 concentration of cisplatin could effectively improve the expression level of RBM17 in mRNA, and knockdown of RBM17 in FaDu cells could enhance the sensitivity of cancer cells to cisplatin." (PMID 36941989, 2023). "Overexpression of DHX15, EIF4A3, and RBM17 splicing factors have been demonstrated in cancer." (PMID 34944912, 2021). "Several studies have reported that RBM17 plays a crucial role in malignant tumor." (PMID 34225773, 2021). "Here, we aspire to explore the influence of RBM17 expression on cancer pathogenesis." (PMID 32497093, 2020). "After screening 12 types of cancer, RBM17 was overexpressed most significantly in HCC." (PMID 32497093, 2020). "In general, high RBM17 expression in HCC cells might be crucial in promoting cancer cell proliferation and preventing apoptosis." (PMID 32497093, 2020). "Based on 6,136 clinical samples, RBM17 was markedly overexpressed in most cancers, especially HCC." (PMID 32497093, 2020). "After comparing the expression level of the tumour and non-tumour tissues, the results indicated that RBM17 was overexpressed in most cancers, and only HCC manifested significantly different expression (P-value < 0.05)." (PMID 32497093, 2020). "However, different from this study, they mainly studied the regulation of RBM17 on cancer cell cycle and apoptosis and did not involve in the migration and invasion of cancer cells." (PMID 36941989, 2023).
tumor (13 papers, 2016 to 2025). "We observed that RBM17 was upregulated in tumor tissues and associated with poor progression." (PMID 36941989, 2023). "FCM showed that knockdown of RBM17 inhibited the infiltration of M2 macrophages in tumor tissue, but promoted the infiltration of CD8+ T cells." (PMID 40702000, 2025). "This discovery underscores the significance of RBM17 in tumor immunology and growth, suggesting its potential as a target for future therapeutic strategies." (PMID 40702000, 2025). "We also analyzed the liver tissue of HCC patients and found that the expression of RBM17 was positively correlated with tumor size and AFP value, indicating its potential role in HCC progression and poor prognosis." (PMID 40702000, 2025). "To validate the role of MSI2 and RBM17 in radioresistance, we constructed stable transgenic cell lines with knockdown of MSI2 and RBM17 and overexpressed another molecule in the knockdown cell line, and nude mice were tumor‐loaded subcutaneously." (PMID 38645664, 2024). "First, we applied the TCGA and GTEx datasets to evaluate the expression of RBM17 in tumor tissues and normal tissues by the GEPIA." (PMID 36941989, 2023). "Downregulation of RBM17 significantly inhibited tumor growth and reduced tumor burden, relative to the control mice." (PMID 36941989, 2023). "We first analyzed the difference of RBM17 expression between tumor and normal tissues using GEPIA and CPTAC databases." (PMID 36941989, 2023). "The RBM17 protein level in PTC tumor tissues was significantly increased compared to its level in ATs." (PMID 34225773, 2021). "The expression values of 185 samples from three GEO queries also confirmed that RBM17 expression in tumour tissues was higher than that in non-tumour tissues." (PMID 32497093, 2020). "Previous studies have shown that RBM17 is overexpressed in tumours, and its silencing can reduce hypopharyngeal carcinoma and glioma cell proliferation." (PMID 32497093, 2020). "Our study underscores the critical role of the RBM17 factor in HCC tumor metabolism and growth." (PMID 40702000, 2025). "For instance, RNA-binding motif protein 17 (RBM17) expression in tumor samples could be used to predict the clinical efficacy of ICI monotherapy in NSCLC patients with a low PD-L1 expression." (PMID 38390262, 2024). "For the non‐irradiated tumors, we found that knockdown of MSI2 and RBM17 could significantly inhibit tumor growth." (PMID 38645664, 2024). "Compared to normal tissues, RBM17 transcript levels were significantly increased in tumor tissues." (PMID 36941989, 2023). "In addition, downregulation of RBM17 effectively suppressed tumor cell migration and invasion through the reversion of epithelial–mesenchymal transition." (PMID 36941989, 2023). "We found that knockdown of RBM17 significantly slows tumor growth compared with control mice." (PMID 36941989, 2023). "In addition, the CPTAC dataset displayed increasing level of RBM17 protein in the primary tumor tissues." (PMID 36941989, 2023). "In the present study, we also assessed whether downregulation of RBM17 can effectively inhibit tumor growth in FaDu HSCC xenograft mouse models." (PMID 36941989, 2023). "Moreover, downregulation of RBM17 could significantly slow tumor growth in FaDu xenograft tumor model." (PMID 36941989, 2023). "Therefore, we hypothesized that tiRNA-Gly displayed a strong tumor-promoting effect on PTC through inducing alternative splicing via the tiRNA-Gly-RBM17 interaction." (PMID 34225773, 2021). "Although RBM5, RBM17, and RBM39 belong to the RNA-binding motif (RBM) family protein, their regulatory role in tumor progression is largely variable." (PMID 38216972, 2024). "The interaction of RNA‐binding motif protein 17 (RBM17) with MSI2 was identified through immunoprecipitation‐mass spectrometry (IP‐MS), revealing its involvement in DNA damage repair and tumor development." (PMID 38645664, 2024).
tumor (continued). "The results showed that the expression of RBM17 was significantly increased in HNSCC tumor tissues, and the prognosis of HNSCC patients with high expression of RBM17 was poor." (PMID 36941989, 2023). "Given its relevance to DNA damage repair and tumor development, similar to our study on MSI2, we found it intriguing and chose to delve deeper into understanding the relationship, functions, and mechanisms between MSI2 and RBM17." (PMID 38645664, 2024). "We found that knockdown of either MSI2 or RBM17 had significant radiosensitizing effects, and MSI2 partially reversed the effect of knockdown of RBM17 on tumor radiosensitivity, while RBM17 significantly reversed the effect of knockdown of MSI2 on tumor sensitivity." (PMID 38645664, 2024). "We presumed that it may make a positive feedback in tiRNA-Gly/RBM17/MAP4K4 axis and may accelerate the tumor-promoting role of tiRNA-Gly in PTC." (PMID 34225773, 2021). "However, studies on RBM17 in tumor radiosensitivity have not been reported yet." (PMID 38645664, 2024).
RBM17 also shares sentences with these, for which no sentence is quoted: colorectal cancer (2 papers); rheumatoid arthritis (2); breast carcinoma (1); cervical carcinoma (1); colon cancer (1); erythroleukemia (1); Lupus Erythematosus Systemic (1); multiple sclerosis (1); neurological disorders (1); triple-negative breast carcinoma (1); type 1 diabetes (1).